EGFR (epidermal growth factor receptor)
Diseases named in the same sentence as EGFR in open-access papers (continued):
Sharing a sentence is not in itself a finding about the gene and the disease.
contact dermatitis (1 paper, 2017). An inflammatory skin condition caused by direct contact between the skin and either an irritating substance or an allergen. "EGFR inhibitors were reported to enhance immediate contact dermatitis and skin hypersensitivity in the 2,4-dinitro uorobenzene (DNFB) induced mouse skin model." (PMID 29069801, 2017).
coronary atherosclerosis (1 paper, 2023). Atherosclerosis of the coronary vasculature. "As a highly selective inhibitor of SGLT-2, CANA reduces endothelial injury to slow coronary atherosclerosis by reducing ROS production and blocking oxidative stress signaling pathway (EGFR/Src/Rho-kinase) mediated by ROS." (PMID 37966667, 2023).
coronary stenosis (1 paper, 2021). Narrowing of the coronary artery lumen diameter. "EGFR declines may be following by the increase of severity of coronary stenosis." (PMID 34938788, 2021).
cribriform carcinoma (1 paper, 2018). A carcinoma characterized by the presence of a cribriform architectural pattern. "Cribriform carcinoma comprises only epithelial cells and no basement membrane-like materials in the spaces and usually expresses ER and PR, whereas ACC of the breast usually does not express ER, PR, and HER2 and tends to express CK5/6 or EGFR and EGFR is potentially an important therapeutic target." (PMID 30189404, 2018).
cryptococcosis (1 paper, 2025). An acute or chronic, localized or disseminated infection by Cryptococcus neoformans. "We report a case of pulmonary cryptococcosis that developed during EGFR-TKI and corticosteroid therapy, highlighting the diagnostic challenges posed by atypical serological findings and the importance of early histopathological evaluation." (PMID 40502915, 2025). "Functional suppression of Th1-type responses due to EGFR-TKI therapy could have contributed to the development of cryptococcosis." (PMID 40502915, 2025).
cryptorchidism (1 paper, 2024). The failure of one or both testes of a male fetus to descend from the abdomen into the scrotum during the late part of pregnancy. "Therefore, EGFR expressions may correlate with age and cryptorchidism." (PMID 38255715, 2024).
deafness (1 paper, 2025). An inherited or acquired condition characterized by the complete loss of the ability to hear from one or both ears. "Previous research has identified EGFR inhibitors as potential targets for noise-induced deafness, offering protection against noise-induced hearing loss by inhibiting the EGFR signaling pathway." (PMID 40248074, 2025).
Dengue hemorrhagic fever (1 paper, 2020). A serious condition caused by Dengue virus infection. "It is possible, however, that vandetanib inhibition of EGFR or VEGFR in vivo may alleviate some of the pathology of dengue hemorrhagic fever and dengue shock syndrome; VEGFR signaling directly induces vasodilation." (PMID 33173007, 2020).
dermal neurofibroma (1 paper, 2008). A dermal neurofibroma is a neurofibroma that occurs in situ of the skin. "EGFR RNA was also quantified by RT-PCR in 20 other MPNSTs and 14 dermal neurofibromas." (PMID 18769552, 2008).
dermatophytosis (1 paper, 2014). A common fungal infection of the stratum corneum of the skin, hair, or nails by a dermatophyte. "A failure to adequately induce AMP to fight off dermatophytes may be responsible for the development of dermatophytosis as seen in patients with anti-EGFR treatment." (PMID 24747887, 2014).
diaphragmatic hernia (1 paper, 2021). A congenital or acquired weakness or opening in the diaphragm which allows abdominal contents to protrude into the chest cavity; congenital diaphragmatic hernias are caused when the embryonic diaphragm fails to fuse. "We consider that regression of the diaphragmatic metastasis by EGFR-TKI therapy resulted in perforation of the diaphragm, causing the diaphragmatic hernia." (PMID 34306720, 2021).
disc degeneration (1 paper, 2017). "This study suggests that targeting the EGFR pathway may be of crucial importance in the preventive treatment of disc degeneration that leads to chronic low back pain." (PMID 28819180, 2017). "Stimulation by thrombin upregulates EGFR-dependent CXCL8 expression through the Src/ERK/STAT3 signaling pathways in NP cells, which may contribute to immune cell recruitment and disc degeneration." (PMID 28819180, 2017).
Duodenal polyposis (1 paper, 2019). Presence of multiple polyps in the duodenum. "DEGs with therapeutic potential include SPP1, which is involved in both cyclooxygenase and epidermal growth factor receptor pathways targeted by the sulindac/erlotinib combination for duodenal polyposis." (PMID 31211760, 2019).
dysplastic cerebellar gangliocytoma (1 paper, 2023). "Reference: This genomic alteration has been described in a case report of Lhermitte-Duclos disease, also known as dysplastic cerebellar gangliocytoma, which has been shown to be an activation mutation resulting in increased EGFR autophosphorylation and indicating high receptor activation." (PMID 36629526, 2023).
ear neoplasm (1 paper, 2015). A neoplasm (disease) that involves the ear. "Mutant EGFR was selectively expressed in the ear tumors, whereas SP-C was expressed in both ear tumors and grossly normal lung tissue, suggesting that SP-C-driven rtTA induces mEGFRL+T-driven tumorigenesis in the ear." (PMID 26027747, 2015). "In summary, we characterized a novel mouse model and human ear tumor specimens to identify EGFR as a molecular target for aggressive ear tumors." (PMID 26027747, 2015). "The effectiveness of EGFR inhibitors in this mouse model supports clinical trials of EGFR inhibitors in humans with aggressive ear tumors." (PMID 26027747, 2015). "Combined with the detection of active EGFR in human specimens of aggressive papillary ear tumors, these studies identify EGFR as a new molecular target for these rare ear neoplasms." (PMID 26027747, 2015). "Taken together, these data indicate that ear tumors in SP-C/mEGFRL+T mice are dependent upon EGFR activation, and that EGFR inhibitors can have pharmacodynamic effects in tumors that are located in the middle ear." (PMID 26027747, 2015). "Because WZ4002 can inhibit EGFR and shrink mEGFRL+T-driven lung tumors, ear tumor-bearing mice were treated with WZ4002." (PMID 26027747, 2015). "EGFR activation was also observed in human ear neoplasms, which provides clinical relevance for this mouse model and rationale to test EGFR-targeted therapies in these rare neoplasms." (PMID 26027747, 2015). "EGFR-directed therapies corrected vestibular defects, induced ear tumor regression, and inhibited EGFR." (PMID 26027747, 2015). "The detection of active EGFR in these specimens raises the possibility that EGFR-targeted therapies might have clinical efficacy in these rare ear neoplasms." (PMID 26027747, 2015). "It is possible that the short latency of lung tumors induced by mutant EGFR in these studies may have masked development of ear tumors that would have occurred had the mice lived longer." (PMID 26027747, 2015). "Next, we evaluated activation of EGFR and downstream pathways in the ear tumors." (PMID 26027747, 2015). "This indicates that EGFR-targeted therapies can be delivered to the complicated structures of the middle ear and temporal bones, raising the possibility that ineffective drug delivery might not limit human application of EGFR-targeted therapies for ear tumors." (PMID 26027747, 2015). "Because ear tumors developed in SP-C/mEGFRL+T mice, but not in lung Clara-cell CCSP-driven mutant EGFR mice, we hypothesized that the expression of both SP-C and mEGFRL+T might be involved in ear tumorigenesis." (PMID 26027747, 2015).
eccrine carcinoma (1 paper, 2012). An adenocarcinoma with eccrine differentiation arising from the sweat glands. "The role of EGFR inhibitor therapy in apocrine-eccrine carcinomas with protein overexpression remains unclear." (PMID 23056620, 2012). "However, studies on genetic alterations and EGFR and Her2 status of apocrine-eccrine carcinomas are few in number." (PMID 23056620, 2012). "With the exception of the tumors associated with familial syndromes, studies on genetic alterations and biomarkers such as epidermal growth factor receptor (EGFR) and HER2 status of apocrine-eccrine carcinomas are few in number." (PMID 23056620, 2012).
Ehrlich tumor (1 paper, 2025). "Thus, we investigated whether the EGFR inhibitor Nano-Gefitinib bilosome decreases Ehrlich tumor cells in a murine model, given that EGFR has been linked to carcinoma–macrophage crosstalk." (PMID 41304988, 2025).
endometrioid tumor (1 paper, 2015). A benign, borderline, or malignant epithelial tumor of the female reproductive system characterized by the presence of glands and/or cysts lined by neoplastic cells that resemble endometrial cells. "Collectively, these results prompted us to further investigate the significance of EGFR in the proliferation of low-grade endometrioid tumor." (PMID 26673416, 2015).
Erdheim-Chester disease (1 paper, 2015). "A patient with Erdheim-Chester disease had an EGFR T790M mutation not previously identified in FFPE tumor samples." (PMID 25980577, 2015).
erythroplakia (1 paper, 1994). "Two of the tumour-derived cell lines and the two erythroplakia-derived cell strains expressed EGFR at levels similar to that detected on normal keratinocytes in tissue culture." (PMID 8080726, 1994). "In this study we determined EGFR expression on a new series of head and neck SCC (SCCHN)-derived cell lines, which were obtained from tumours representing a spectrum of malignant progression, and two cell strains derived from erythroplakia premalignant lesions." (PMID 8080726, 1994).
Fulminant hepatic failure (1 paper, 2020). Hepatic failure refers to the inability of the liver to perform its normal synthetic and metabolic functions, which can result in coagulopathy and alteration in the mental status of a previously healthy individual. "FGL1 accelerates hepatocyte proliferation and protects against liver injury by activating the EGFR/ERK cascade through the Src-dependent pathway, exhibiting its potential to be used to treat fulminant hepatic failure in humans." (PMID 33123164, 2020).
germ cell neoplasm (1 paper, 1991). "In comparison with normal DNA, tumour DNA of a total of eight patients (seven with germ cell neoplasm and one with testicular lymphoma) showed increased dosages of KRAS2, PDGFA, EGFR, MET and PDGFB." (PMID 1829952, 1991).
giant cell carcinoma of the lung (1 paper, 2017). "However, there is no confirmed evidence describing giant cell carcinoma of the lung in terms of its epidemiological features, including the EGFR mutation rate, or therapeutic efficiency to EGFR-TKIs of patients with sensitive EGFR mutations." (PMID 28445978, 2017). "Among NSCLC, giant cell carcinoma of the lung (GCCL) is a rare pathological subtype with poor prognosis, with no confirmed evidence about its epidemiological features or therapeutic efficiency of EGFR-TKIs." (PMID 28445978, 2017).
gingival cancer (1 paper, 2014). A primary or metastatic malignant neoplasm that affects the gums. "Despite the augmented HLA-DR expression on a gingival cancer cell line by EGFR inhibition, anti-tumor responses of EGFR reactive helper T cell clones against tumor cells were decreased." (PMID 25240937, 2014).
gingivitis (1 paper, 2023). A disorder involving inflammation of the gums; may affect surrounding and supporting structures of the teeth. "EGFR is highly expressed in epithelial and stromal cells of inflamed gingiva of patients with gingivitis, whereas no or low expression in healthy gingiva." (PMID 37083725, 2023).
glucose metabolism disorders (1 paper, 2025). "The epidermal growth factor receptor (EGFR) is known to be a key factor in glucose metabolism disorders due to its ability to inhibit insulin receptor activity upon activation." (PMID 40863931, 2025).
gonococcal infection (1 paper, 2009). "Our data showing EGFR degradation in ME180 cells upon meningococcal infection contrast with previous data on gonococcal infection of HEC-1-B and A431 cells showing EGFR accumulation." (PMID 19718432, 2009).
gram-negative bacterial infections (1 paper, 2025). Infections caused by bacteria that show up as pink (negative) when treated by the gram-staining method. "The role of dendritic cells was noteworthy considered in Gram-negative bacterial infections triggering the cytokine, Interleukin, GPCR, IFN, FLT3, EGFR, G alpha, Receptor tyrosine kinase, and TLR signaling pathways and exacerbating their activities by the MQs and VSMCs in vessel microenvironment." (PMID 40275124, 2025).
Gynecomastia (1 paper, 2013). Abnormal development of large mammary glands in males resulting in breast enlargement. "We found that expression patterns in gynecomastia were largely comparable with normal female breast tissue; i.e. no expression of HER2, EGFR, MET, GLUT1 and CAIX detectable." (PMID 23308200, 2013).
hamartoma (1 paper, 2018). A benign and excessive tumor-like growth of mature cells and normal tissues which grow in a disorganized pattern. "That article described the discovery of epidermal growth factor receptor (EGFR) exon 20 insertion/duplication mutations in 12 cases of FHI, casting a cloud over their status as true “hamartomas” and suggesting that the distinction from neoplasia may be arbitrary." (PMID 30613391, 2018).
hemangioma (1 paper, 2021). A benign vascular lesion characterized by the formation of capillary-sized or cavernous vascular channels. "As expected, we also found that lymphatic endothelial hyaluronan receptor-1 (LYVE1) and RTKs, such as EGFR, HER2, and HER3, were highly expressed in proliferating hemangiomas." (PMID 33400686, 2021).
hemorrhagic fever (1 paper, 2022). An infectious disease caused by certain viruses or bacteria that can damage the walls of tiny blood vessels, making them leak, and can hamper the blood's ability to clot and cause severe, life-threatening illness. "Since AG1478 completely inhibited EGFR activity at low μM range, its EGFR inhibitory activity was not likely responsible for the antiviral activity against these hemorrhagic fever viruses." (PMID 35628375, 2022).
hemorrhagic stroke (1 paper, 2018). A stroke caused by a bleed on the brain. "In ischemic and hemorrhagic stroke, dual effects of several EGFR/ErbB ligands are noteworthy." (PMID 29342116, 2018).
hepatocellular adenoma (1 paper, 2016). A benign epithelial neoplasm arising from the hepatocytes. "Activation of the epidermal growth factor receptor (EGFR) signaling pathway promotes the development of hepatocellular adenoma (HCA) and carcinoma (HCC)." (PMID 27669229, 2016).
hereditary cancer (1 paper, 2022). Malignant neoplasms occurring in families at a rate greater than that expected by chance and caused by germline mutations in a specific gene. "However, EGFR mutations are not conventional germline mutations associated with hereditary cancers, and are not common in our cohort as well." (PMID 35596192, 2022).
hypercalcaemia (1 paper, 2007). "Epidermal growth factor receptor signalling is likely to play different roles in the control of PTHrP gene expression and generation of hypercalcaemia by the two cell lines." (PMID 17533397, 2007). "To determine if both cell lines would be suitable for future studies with EGFR-targeted therapeutics, we compared the onset of hypercalcaemia, plasma PTHrP concentrations, tumour PTHrP mRNA expression and EGFR phosphorylation status in subcutaneous tumours of nude mice." (PMID 17533397, 2007). "Therefore, both cell lines produced tumours with activated EGFR, secreted high concentrations of PTHrP, and induced hypercalcaemia." (PMID 17533397, 2007). "We have established that the EGFR ligand, AREG, stimulated EGFR signalling and PTHrP gene expression in two human lung SCC lines that induce hypercalcaemia when grown in vivo." (PMID 17533397, 2007).
Hyperkalemia (1 paper, 2020). An abnormally increased potassium concentration in the blood. "Besides the promotion of calcium, LSCC also activates multiple genes that produce hyperkalemia, including EGFR, EZH2." (PMID 33092550, 2020).
hyperplasia (1 paper, 2022). An abnormal increase in the number of cells in an organ or a tissue with consequent enlargement. "Leukocyte-derived cytokines, including TNF-α, were reported to be potent inducers of epidermal growth factors (EGF) and receptor (EGFR), which attributed to epidermal hyperplasia and thickening in chronic skin disorders." (PMID 36204219, 2022).
hyperplastic polyp (1 paper, 2017). A polyp found mainly in the stomach and colon. "Hyperplastic polyps (HP) (n = 8) and control colons (n = 53) were EGFR negative in half of cases (p < 0.0001)." (PMID 28157706, 2017).
hypertensive nephropathy (1 paper, 2024). Kidney damage that results from chronically elevated blood pressure; complications include glomerular damage resulting in proteinuria and hematuria. "Summary of selected studies highlighting the role of EGFR signalling in hypertensive nephropathy." (PMID 39234105, 2024).
hypophosphatemia (1 paper, 2024). Lower than normal levels of phosphates in the circulating blood. "In addition, hypophosphatemia has been reported in patients treated with EGFR inhibitors." (PMID 39026680, 2024).
IgA nephropathy (1 paper, 2023). "For instance, recent reports suggest that gefitinib, an epidermal growth factor receptor (EGFR) inhibitor, can trigger diverse renal kidney pathologies including MCD, tubulo-interstitial nephritis (TIN), membranous nephropathy (MN) and IgA nephropathy (IgAN)." (PMID 37675354, 2023).
ileus (1 paper, 2019). Decrease in peristalsis in the absence of a mechanical bowel obstruction. "Therefore, we suggest that even if the primary focus is the right-sided colon, an anti-EGFR antibody plus CAT should be introduced for mCRC patients who require quick and marked reduction of metastatic lesions that cause concomitant symptoms such as ileus or pain." (PMID 31103951, 2019).
immunotoxicity (1 paper, 2025). "Notably, 44 targets, including EGFR, AKT1, PIK3R1, PTEN, and mTOR, were mapped to the PI3K-Akt signaling pathway, highlighting its potential association with celastrol-induced immunotoxicity." (PMID 40495892, 2025).
infectious mononucleosis (1 paper, 2023). A condition characterized by an increase in mononuclear white blood cells and swollen lymph nodes, which is usually caused by infection with the Epstein-Barr virus. "However, the role of the AREG/EGFR/HIF-1α pathway in regulating interleukin-9 (IL-9) production by T cells in adult patients with infectious mononucleosis (IM) has not been fully elucidated." (PMID 36154925, 2023).
intracranial aneurysm (1 paper, 2022). "Pharmacological inhibition of EGFR by erlotinib attenuates intracranial aneurysm through regulating phenotype of vascular smooth muscle cells." (PMID 34729926, 2022). "The expression of p‐EGFR was distributed in most intracranial aneurysm wall layers." (PMID 34729926, 2022). "Epidermal growth factor receptor (EGFR) activation was found in human intracranial aneurysm tissues and rat intracranial aneurysm models." (PMID 34729926, 2022).
ischemia reperfusion injury (1 paper, 2022). Adverse functional, metabolic, or structural changes in ischemic tissues resulting from the restoration of blood flow to the tissue (reperfusion), including swelling; hemorrhage; necrosis; and damage from free radicals. "The epidermal growth factor receptor (EGFR or ErbB1) ligand AREG has been identified to induce activation of the survival kinases Akt in the myocardium to protect against ischemia-reperfusion injury." (PMID 36009485, 2022).